RET (ret proto-oncogene)
Diseases named in the same sentence as RET in open-access papers (continued):
Sharing a sentence is not in itself a finding about the gene and the disease.
tumor (continued). "To understand this finding, we might hypothesize that the primary tumor is composed of RET-positive and RET-negative cell subpopulations." (PMID 29515777, 2018). "Excitingly, several recent studies in preclinical animal models have suggested that targeting RET function could both limit tumor growth and resensitize tumors to endocrine therapies, prolonging the efficacy of these agents." (PMID 30666215, 2018). "Patient ID0110M’s tumor cells (with the p.Cys630=;Cys634Arg phenotype) thus appeared to contain higher levels of RET mRNA, and this alteration resulted in more abundant activated RET protein than that found in a p.Cys634Arg MTC." (PMID 30321177, 2018). "We can therefore conclude that, for patients with true sporadic MTC without germline RET mutations having a solitary MTC tumor confined in a lobe, total thyroidectomy was not needed, and hemithyroidectomy was adequate as a locally curative surgery." (PMID 30051240, 2018). "We examined the viability of RET-fusion-positive human tumor cell lines." (PMID 29088743, 2017). "Since RET is essential for NB cell proliferation, we then hypothesized that its small molecule inhibitor regorafenib would have an anti-tumor effect on NB." (PMID 29262623, 2017). "Most hyper-functioning tumors harbor both TSHR mutations and proto-oncogene mutations; this coexistence suggests that carcinomas arise from the activity of classical oncogenes, such as RAS and RET/PTC, and that the TSHR and Gs mutations contribute to the hyper-functioning features of the neoplasms." (PMID 28117293, 2017). "In sporadic MTC without RET mutations, 69.2% of tumor samples show RAS mutations that can activate RAS/RAF/ERK and PI3K/AKT/mTOR pathways." (PMID 28476040, 2017). "Furthermore, Sorafenib (BAY 43–9006), a multi-kinase inhibitor also targeting RET, has potent anti-tumor activity in HCC clinical trials." (PMID 26675549, 2016). "Western blot analysis of RET in protein extracts from three MLS cell lines showed reactive bands at 170 kDa, the reported size for the longest RET isoform, and immunohistochemical (IHC) analysis of tumor tissues detected RET protein in both nuclei and cytoplasm of most tumor cells." (PMID 26595521, 2016). "To further explore the therapeutic potential of the NDI, we assessed its cytotoxic activity in an in vitro model of estrogen-receptor positive breast cancer (BCa), a tumor type for which anti-RET therapy may represent a novel treatment option." (PMID 27351133, 2016). "Such hetero-complex formation and activation of RET may operate in MLS cells as EGFR is strongly expressed in the tumor cells." (PMID 26595521, 2016). "Specimens with expression of >110% RET cytoplasm were categorised as high RET cytoplasmic expression tumours, and specimens with expression of >80% RET nucleus were categorised as high RET nuclear expression tumours." (PMID 27092013, 2016). "Furthermore, inhibiting either RET signaling or ER signaling (either by blocking E2 production or promoting ER degradation) is comparable in reducing primary tumor growth." (PMID 27602955, 2016). "Both RET-mice and a Mel-ret murine melanoma cell line from the tumor of a RET-mouse might be strong tools for analyzing the molecular mechanism of melanoma growth." (PMID 26506241, 2016). "Thus NF1, VHL, RET, and MAX germline and somatic mutations have been reported in 3–25%, 13–9%, 5–5%, and 1–3% of tumours, respectively." (PMID 25883647, 2015). "Seven tumor samples were positive for RET rearrangements (vandetanib, n = 3; comparator, n = 4)." (PMID 25881079, 2015). "The prevalence of RET Y791F in the control databases was extremely high compared with the 40 known RET pathogenic mutations (P=0.00003), while no somatic occurrence has been reported in tumours." (PMID 25425582, 2015). "In two cases, RET was only detected in the focal areas of tumor cells." (PMID 25881079, 2015).
tumor (continued). "2.8% (n = 26) of samples had RET amplification (innumerable RET clusters, or ≥7 copies in > 10% of tumor cells), 8.1% (n = 76) had low RET gene copy number gain (4–6 copies in ≥40% of tumor cells) and 8.3% (n = 92) were RET expression positive (signal intensity ++ or +++ in >10% of tumor cells)." (PMID 25881079, 2015). "In accordance with our data on elderly individuals carrying RET Y791F without any history of tumours, a recent study that analysed the exome data of 44 centenarian Ashkenazi Jews has found two individuals (2/44=0.045) harbouring the RET Y791F variant." (PMID 25425582, 2015). "A number of studies have reported increased expression of RET protein in NSCLC tumor cells, not necessarily associated with RET rearrangements." (PMID 25881079, 2015). "Regorafenib (BAY 73-4506) binds to and inhibits VEGFR-1, - 2 and -3, and tumor cell signaling kinases (RET, KIT, PDGFR, and Raf), which may result in the inhibition of tumor angiogenesis and tumor cell proliferation." (PMID 25884155, 2015). "In vitro data suggested that the siRNA RET/PTC3 could have therapeutic effects if administrated to tumours carrying RET/PTC3 junction oncogene." (PMID 24759995, 2014). "In summary, our data suggest that the RET S836S polymorphism in exon 14 and the GGTC haplotype are risk factors for PTC and that the G691S/S904S polymorphisms might be associated with tumour behaviour." (PMID 25330015, 2014). "After intravenous injection in nude mice, respective squalene (SQ) nanoparticles (NPs) of siRNA RET/PTC3 significantly (p<0.001) reduced RP3 tumour growth, oncogene and oncoprotein expressions, induced apoptosis and partially restored differentiation (decrease in Ki67)." (PMID 24759995, 2014). "In vivo on mice xenografted RP3 cells, siRNA RET/PTC3-SQ NPs were found to: i) inhibit tumour growth, ii) reduce RET/PTC3 oncogene and oncoprotein expressions, iii) induce cell death (cleavage of both caspase-3 and PARP-1) and iv) partially restore differentiation (decrease of Ki67 marker)." (PMID 24759995, 2014). "Furthermore, somatic rearrangements of the RET gene are associated with PTC and commonly seen in childhood tumours and those associated with radiation exposure." (PMID 25330015, 2014). "This hypothesis may be an important strategy in tumours where an inflammatory response could increase the expression of the molecular players involved in RET–IL-6 crosstalk." (PMID 24467886, 2014). "The various tumor components of MEN-2 are all thought to be products of RET proto-oncogene mutation which convert the RET proto-oncogene into a dominant transforming gene, while the non-mutated allele is retained in the tumor." (PMID 23455356, 2013). "A different study on 49 MTC confirmed that Ras mutations are a rare event in this type of tumor, regardless of RET mutational status." (PMID 23509459, 2013). "We assessed whether patient ACC tumor specimens express RET, the cognate receptor for GDNF, using immunohistochemical staining." (PMID 22768171, 2012). "The chromosomal changes 6p-, 16p-, 18p + could determine in part the oncogenic phenotype in the primary M918T RET positive tumor and probably related to persistence of high serum CT levels in this patient." (PMID 22676344, 2012). "Recent researches suggest that an overrepresentation of mutant RET as a “second hit” event might trigger tumor genesis." (PMID 23093970, 2012). "Analysis of TPO and TG expression levels, among tumors, according to the subtype of molecular alteration identified, conducted to the observation that the tumor sample presenting both the RET/PTC3 rearrangement and the p.A67G showed the lowest TPO expression level amongst all tumor samples." (PMID 22481925, 2012). "It targets key signalling pathways in cancer by inhibiting vascular endothelial growth factor receptor (VEGFR)-dependent tumour angiogenesis, and epidermal growth factor receptor (EGFR), and rearranged during transfection (RET)-dependent tumour cell proliferation and survival." (PMID 22363427, 2012).
tumor (continued). "The matter could be further clarified by correlation of RET rearrangements with disease duration, tumor size, histologic grade, and certain tumor phenotypes." (PMID 22175034, 2012). "Given the significant decrease in the vascularity of AZD1480- treated tumors and consequent tumor necrosis, we suggest that phospho-STAT3 inhibition in the microenvironment (endothelial cells) cooperates with RET inhibition in cancer cells to induce tumor regression." (PMID 23056499, 2012). "Somatic RET mutations are not consistently distributed within primary tumours and metastases, indicating that the mutation can occur during progression of the tumour or that MTC is a disease of polyclonal origin." (PMID 22654561, 2011). "Our analysis suggested the tumor cells were driven by the RET oncogene." (PMID 20696054, 2010). "By its capacity to block activation of endothelial cells therefore, HB-19 could impair tumor vascularization in RET mice." (PMID 20573279, 2010). "However, the low rate of tumour formation encountered in our study of the E7 or RET/PTC3 models differed from previous studies." (PMID 18985036, 2008). "However, if the distribution of cells harbouring a RET rearrangement within tumours are considered, remarkable differences between tumours of differing latencies become apparent." (PMID 16641909, 2006). "Abnormal expression of PTK genes, such as insulin-like growth factor receptor (IGF-IR), epidermal growth factor receptor (EGFR), focal adhesion kinase (FAK), or the proto-oncogenes RET and NyK/mer, has been shown to correlate with progression in a variety of tumours." (PMID 12698188, 2003). "This association between RET/PTC and the allele A2 may contribute to a CCH observed in peritumoural tissues of these tumours." (PMID 12085189, 2002). "The absence of somatic RET mutation data from tumor samples represents another limitation, as these mutations may provide additional prognostic information in sporadic cases." (PMID 40731793, 2025). "This suggests that RET may preferentially promote nonmalignant or exophytic tumours rather than aggressive invasive variants." (PMID 40211435, 2025). "However, it cannot be excluded that the coexistence of NRAS and RET alterations in this case is due to the presence of heterogeneous tumor populations derived from two distinct tumor foci colliding in the same lesion, a possibility well described in the literature." (PMID 41123735, 2025). "RET gene fusions are more frequently found in non-smokers, younger patients, and those with non-squamous histology, and are associated with a higher incidence of brain metastases and a low-immune-infiltration tumor microenvironment." (PMID 40606448, 2025). "Abnormal activation of RET (via mechanisms such as gene rearrangements or point mutations) can activate key downstream signaling pathways such as the RAS/MAPK and PI3K/AKT pathways, driving tumor cell proliferation, survival, invasion, angiogenesis, and metastasis." (PMID 41278287, 2025). "Regarding SCNAs, we could not find significant correlation between the number of SCNAs per tumor or the presence of chromosome 22 and 9 losses with a worse outcome, independent of the presence of a RET variant (P = .77)." (PMID 38655100, 2024). "In tumour tissue in which no RET mutation is found, a RAS mutation can often be detected." (PMID 38919477, 2024). "Finally, we highlight a talin 1 and 2 (TLN1 and TLN2) PTB binding site in the proto-oncogene tyrosine-protein kinase receptor Ret (RET), which is disrupted by two mutations (L1061P, Y1062A) linked to multiple endocrine neoplasia type 2 and to different types of tumours." (PMID 39009827, 2024). "Similarly, RET L881V-driven tumours are resistant to lenvatinib, cabozantinib and vandetanib due to absence of a phenyl ring required for binding, and presence of this phenyl ring on RET L730V confers resistance to nintedanib, due to a hydrophobic interaction." (PMID 39001359, 2024).
tumor (continued). "In-depth knowledge of the advantages and disadvantages of the different RET testing methodologies could help clinical and molecular tumor boards implement and maintain sensible algorithms for the rapid and effective detection of RET fusions in patients with NSCLC." (PMID 38525319, 2024). "Although the MAX mutation is classified as type C2, including RET, NF1, TMEM127,H-RAS and ATRX, which belongs to the SWI/SNF family of chromatin remodeling proteins, as their upregulation will activate the PI3K/AKT and RAS/MAPK signaling pathways resulting in tumor formation." (PMID 39279998, 2024). "In our study, tumor tissues from 83 PTC patients were investigated to determine the prevalence of CCDC6::RET and NCOA4::RET rearrangements in Thailand and to explore the association between the mRNA expression of CCDC6::RET and NCOA4::RET rearrangements and clinicopathology." (PMID 37188126, 2023). "However, clinical trials are currently being conducted to assess the safety and efficacy of selpercatinib in a heterogeneous patient population with advanced solid tumors carrying RET fusion, other than in the lungs or thyroid, representing a tumor-agnostic population." (PMID 38001751, 2023). "Importantly, two patients (2.4%) were treated with sorafenib, lenvatinib, and then NTRK inhibitors, and one patient (1.2%) was treated with lenvatinib as first-line therapy and then with a RET inhibitor, according to the molecular profile of the patient’s tumor." (PMID 37879236, 2023). "In agreement with the literature data, while RET-rearranged advanced NSCLC seems to be responsive to classic platinum-based cytotoxic therapy, it appears to be scarcely sensitive to immunotherapy in the form of immune checkpoint inhibitors (being a “cold” tumor with a low tumor mutational burden)." (PMID 36768754, 2023). "When no targetable mutation is identified (NTRK, ALK, RET or BRAF) or the tumor is not sequenced, the antiangiogenic multi-targeted kinase inhibitors (aaMKIs) Sorafenib, Lenvatinib and Cabozantinib may be used." (PMID 37510219, 2023). "Multimodal/combination therapy trials combining several agents with synergistic approaches may provide therapies with more potent clinical utility, such as concurrent inhibition of RET and signalling pathways, or the more general mechanism of tumour progression." (PMID 37207147, 2023). "We hypothesized that if tumorigenesis is regulated by RET signaling, then we should observe a change in tumor burden in ApcMin/+Ret+/− mice that is either decreased compared with ApcMin/+ mice if RET signaling promoted tumorigenesis or increased if RET suppressed tumorigenesis." (PMID 39148929, 2023). "Notably, a total of 10 previously reported single-nucleotide polymorphisms (SNPs) were found in this tumor in genes including MLH1 (rs769364808), FGFR3 (rs769364808), two variants (rs1873778 and rs2228230) in PDGFRA, KIT (rs55986963), APC (rs41115), and RET (rs1800861)." (PMID 37273678, 2023). "Some survey items could not be divided by type of tumour (e.g., medullary or papillary TC) or RET-alteration (e.g., mutation or fusion) in order to keep the survey short." (PMID 37277734, 2023). "Importantly, we found novel protein changes including high levels of oncogenic proteins such as R-Spondin 3 (RSPO3) and secernin 1 (SCRN1) as well as low levels of tumor suppressors such as Ret proto-oncogene (RET) and Rho guanine nucleotide exchange factor 12 (ARHGEF12) in CRC patients." (PMID 37228491, 2023). "Collectively, these data suggest that multiple tumor clones with distinct mitogenic drivers (either RET or KRAS) may co-exist at baseline, each shedding into circulation at different rates, ultimately leading to either short duration of at-best mixed response or primary resistance." (PMID 35304457, 2022). "Therefore, a cell-type specific GFRα2/GFRα3 ratio could indeed determine the tumor promoting vs. tumor suppressing behavior of RET." (PMID 34716856, 2022).
tumor (continued). "Thus, RET fusions present as a clinical and therapeutic challenge in multiple tumor types." (PMID 35957881, 2022). "These tumor agnostic therapies may be relevant also in ATC with RET fusions." (PMID 35872981, 2022). "Similarly, though RET is not a known biomarker in immune oncology, RET does appear to have central roles in directing the tumor microenvironment, promoting cancer-associated inflammation, and suppressing anti-tumor immune responses." (PMID 35798829, 2022). "In addition, in 48B-originating tumor cells a unique mutation was found in PIK3CA, and RET genes." (PMID 36291930, 2022). "The anti-tumor effects of LDD-2633 may be extended to NSCLCs harboring RET fusion proteins." (PMID 33419162, 2021). "Thus, our study suggests that selpercatinib could be an option when pralsetinib-treated cancers progress with L730V/I-positive cfDNA or tumor biopsy for continuing suppression of the RET-altered tumors." (PMID 34099825, 2021). "The activity, albeit reduced, on RET/TRKA-negative tumours may be justified by VEGFR2 inhibition." (PMID 34373541, 2021). "No RET-protooncogene mutation was detected in exons 11,10,13-16 in the tumour tissue." (PMID 34659114, 2021). "Therefore, VEGFR inhibition, though not sufficient to blunt intracellular signalling, may be involved in the reported inhibition of RET/TRKA-negative tumours." (PMID 34373541, 2021). "Our data suggest that the relationship between ALK and RET is complex, involving both transcriptional and post-translational regulation, likely reflecting a delicate interplay of developmental events in the sympathetic nervous system and tumor development that are currently not fully understood." (PMID 33921066, 2021). "Thus, the limitations of these MKIs may prevent potent RET-pathway inhibition and subsequently yield poor pharmacokinetic (PK) properties and weak anti-RET positive tumor efficacy." (PMID 34832869, 2021). "Furthermore, RET rearranged tumours have been linked to certain subtypes of adenocarcinoma, notably lepidic, solid and papillary, both in Asians and in non-Asians." (PMID 34503226, 2021). "Moreover, NGS can also be used to investigate both RNA and DNA tumours and may therefore amplify the RET fusion detection rate." (PMID 34503226, 2021). "Therefore, an anti-tumor effect of CXCR2 inhibition in RET transgenic mice could be mediated by reduced migration of CXCR2+ PMN-MDSC to the tumor, resulting in the accumulation of NK cells." (PMID 33578808, 2021). "MTC is reported to exhibit low PD-L1 expression in both tumor cells and tumor-infiltrating immune cells and no microsatellite instability, irrespective of the presence/absence of either desmoplasia, lymph node metastases and/or RET mutation." (PMID 33935977, 2021). "The RET/GDNF tyrosine-kinase survival pathway could generate tumour promoting proliferative events." (PMID 34588620, 2021). "Although selective RET inhibitors are well tolerated and induce significant and durable tumor responses in heavily pretreated patients with RET-rearranged NSCLC, however, as has been seen with other selective TKIs, the emergence of acquired resistance may limit long-term efficacy." (PMID 33771190, 2021). "Interestingly, it may also cause a secondary resistance to vandetanib, probably related to single tumor cell clones carrying the RET V804 substitution upon a multikinase treatment." (PMID 33112827, 2020). "In summary, the crosstalk between RET and ER is important in the development of endocrine resistance and specifically targeting RET within combination treatment regimens might help to restore endocrine resistance in ER positive tumours." (PMID 30621641, 2019).